CLDN2 (claudin 2)
Diseases named in the same sentence as CLDN2 in open-access papers (continued):
Sharing a sentence is not in itself a finding about the gene and the disease.
tumor (continued). "However, while confirming an essential role for claudin-2 in regulating the tumor cell plasticity and RCC progression, our data also confirms that claudin-2 loss in itself is not oncogenic as claudin-2KO mice do not develop renal tumorigenesis." (PMID 33622361, 2021). "Additionally, changes in claudin-2, -4, and -7 and other TJ proteins, such as ZO-1 and occludin, were found in SCC of the skin, but the association between claudin expression and tumor characteristics has not been analyzed so far." (PMID 36232536, 2022). "While no significant change in primary tumor growth following caecal injection was observed between parental and Cldn2KO HT-29 cells, CRC cells lacking Claudin-2 demonstrated an average 9.3-fold decrease in their spontaneous liver-metastatic potential." (PMID 34079064, 2021). "In GC, paired analysis showed significantly upregulated Ki67 proliferation marker and tight junction protein CLDN2 and downregulated anti-apoptotic BCL2 in tumor as compared to non-cancerous tumor-adjacent tissue." (PMID 32630408, 2020). "Thus, changes in Gast, Ccla3, Glycam1, Spp1, Serpina1a, Cela1, Cldn2, and Fabp2 are a result of GW501516 treatment and are not tumor specific." (PMID 21318167, 2010).
cancer (49 papers, 2009 to 2025). A tumor composed of atypical neoplastic, often pleomorphic cells that invade other tissues. "Parental HT-29 cells display a 2.7-fold higher ability to adhere to primary hepatocyte monolayers when compared to Claudin-2 deficient cancer cells." (PMID 34079064, 2021). "Notably, along with its role in paracellular transport, CLDN2 has been implicated in autophagy, cell proliferation, and migration in IECs as well as cancer stem cell regulation in CRC." (PMID 37815870, 2023). "Increased expression of the gene encoding claudin 2 and 5 is characteristic of cancer." (PMID 35453754, 2022). "CLDN2 is a promising tight junction localized protein with well-characterized functions, including promoting the tumorigenicity, metastasis, and susceptibility of cells to 5-FU, perhaps through ameliorating cancer stem cell property in CRCs." (PMID 35052740, 2021). "Notably, the overexpression of certain claudins like claudin-2 and claudin-4 has been linked with increased malignancy and poor patient outcomes, while others such as claudin-1 show variable associations depending on the cancer subtype." (PMID 39364319, 2024). "Thus, while elevated claudin-2 might protect against injury and enhance regeneration, it could raise the risk of cancer." (PMID 31726679, 2019). "Comparisons with matched primary tumors revealed an upregulation of CLDN2 expression in liver metastases and it was shown that CLDN2 is functionally required for attachment of cancer cells to hepatocytes through trans-homotypic interactions." (PMID 38371623, 2024). "Altogether, it indicates that the expression of CLDN5, CLDN11, CLDN2, CLDN7, and CLDN12 is associated with regulating the key cancer-associated pathways in the COAD and GSEA datasets." (PMID 37799140, 2023). "Claudin-2 (Cldn-2) is a tight junction protein that mediates paracellular water or ion transport and has emerged to play a role in cancer." (PMID 37488117, 2023). "In fact, claudin 2 expression is dysregulated in cancer and inflammation, with a positive correlation between disease stage and claudin 2 abundance." (PMID 36077907, 2022). "The upregulation of CLDN2 expression has been reported in various cancer tissues such as liver, breast, endometrium, and stomach." (PMID 35886884, 2022). "CLDN2 facilitates the tumorigenicity by enabling anchorage-independent growth in the colorectal cancer cells, which is tightly correlated with cancer progression." (PMID 35886884, 2022). "Although experimental and clinical studies have explored the function of CLDN2 in various cancer initiation and development processes, the precise role and underlying mechanism of CLDN2 in CRC remain largely unclear." (PMID 34965023, 2021). "In the context of cancer cells, where TJs and contact inhibition are at least partially lost, overexpression of claudin-2 enhances YAP activity in coordination with other oncogenic signaling networks." (PMID 34354941, 2021). "CLDN2, a component of cellular tight junction, is reported to participate in the progression of various cancers through its expression aberrance." (PMID 34965023, 2021). "In support of a role for claudin-2 in augmenting motility, in various cancer cells claudin-2 overexpression correlates with enhanced migration." (PMID 31726679, 2019). "Claudin-2 expression is dysregulated in many pathologies including cancer, inflammation, and fibrosis." (PMID 31726679, 2019). "One prominent example is the significant correlation between Cdx2 and claudin-2 expression in gastric dysplasia and cancer." (PMID 31726679, 2019). "A multitude of signaling pathways, many of which are pro-proliferative and cancer-related, were shown to affect claudin-2 abundance." (PMID 31726679, 2019). "Accordingly, claudin-2 knockdown impaired cell growth and migration and elevated sensitivity for anti-cancer agents." (PMID 31726679, 2019).
cancer (continued). "As discussed in Section 3.2, many proliferative pathways affect claudin-2 expression, and these are often dysregulated in diseases, including in cancer." (PMID 31726679, 2019). "We now demonstrate that the PDZ-binding motif of Claudin-2 is necessary for anchorage-independent growth of cancer cells and is required for liver metastasis." (PMID 30692208, 2019). "Inhibition of A549 cancer cell migration in a wound-healing assay by claudin-2 knockdown was attributed to reduced MMP-9 expression and activity due to Sp1 inhibition." (PMID 31726679, 2019). "Taken together, these studies provided strong evidence that targeting claudin-2 can mitigate proliferation and raised hope that this approach will prove useful in cancer therapy (see further elaboration in Section 5.4)." (PMID 31726679, 2019). "When the correlation between the claudin-2 expression in cancer cells and in CAFs of the same location was analyzed, low concordance was observed in both CT and IM (g = 0.28, p < 0.001, and g = 0.24, p = 0.001, respectively)." (PMID 29134439, 2018). "The elevation of claudin-2 expression is reported in cancer tissues including lung, liver, colon, and stomach." (PMID 26061016, 2015). "Claudin-2 was found to be one of the factors involved in interactions of cancer cells with cells of the target tissue determining the metastatic spread." (PMID 25598217, 2015). "In the case of Fst and RasGRF1 strong cytoplasmic and nuclear staining was observed, where as the expression of Cldn2 was restricted to the cytoplasm and patchy throughout neighboring cancer cells." (PMID 19812696, 2009). "And it is mainly reported the permeability function of CLDN2 in intestinal diseases and cancer." (PMID 38425650, 2024). "Besides, the expression levels of CLDN2, CLDN7, and CLDN12 are negatively correlated with some of the cancer-associated pathways." (PMID 37799140, 2023). "Clusters of TCF4 binding sites are present in promoters of the CLDN2, CLDN4, CLDN7, and OCLN genes, and these genes could thus be upregulated in cancers with APC mutations." (PMID 37998722, 2023). "Claudin-2 expression is upregulated in multiple cancers and promotes cancer malignancy." (PMID 33622361, 2021). "This is the first report demonstrating that C3G reduces CLDN2 expression in cancer cells." (PMID 33419064, 2021). "Thus, it is conceivable that the Claudin-2 PDZ-binding motif confers early cancer cell survival within the liver." (PMID 34079064, 2021). "However, the most striking cancer-type related difference was associated with the expression of CKDN2, a gene encoding tight junction protein claudin-2." (PMID 32630408, 2020). "This raises the intriguing possibility that elevated claudin-2 expression might be a crucial connection between inflammation and cancer." (PMID 31726679, 2019). "The effects of claudin-2 on cell migration may be relevant in both cancer biology and tissue regeneration." (PMID 31726679, 2019). "Claudin-2 is emerging as a promoter of cancer progression and metastasis." (PMID 30692208, 2019). "Given the importance of the PDZ-binding motif for growth in soft agar and the formation of liver metastases, it is conceivable that the PDZ-binding motif of Claudin-2 may also be required for early cancer cell survival within the liver." (PMID 30692208, 2019). "As mentioned in Section 5.1, claudin-2 levels rise with the development of dysplasia and cancer." (PMID 31726679, 2019). "The following overview however also highlights that the role of claudin-2 is likely complex, and differences in its impact might exist not only based on tissue origin but also cancer stage." (PMID 31726679, 2019). "In agreement with the findings from the SPCRC cohort, a statistically significant association between CAF-associated claudin-2 expression (but not cancer cell-associated claudin-2 expression) and PFS was detected." (PMID 29134439, 2018).
cancer (continued). "The authors suggest that the formation of claudin-2-mediated cell–cell interactions between cancer cells and hepatocytes may entail induction of c-Met and in turn activate the pathways responsible for development of metastasis." (PMID 25598217, 2015). "In addition, CLDN2 affects the proliferation of cancer cells." (PMID 36555089, 2022). "CLDN2 may be involved in the regulation of cancer stem cells in A549 spheroids." (PMID 34205320, 2021). "Glycosaminoglycans have therapeutic value in cancer; tight junction whose protein claudin-2 has been reported as a potential target for CRC therapy; circadian rhythm plays roles in the pathogenesis of CRC; ECM-receptor interaction may play a critical role in CRC metastasis." (PMID 32680494, 2020). "In CRC, claudin-2 (CLDN2) is typically overexpressed and promotes the aggressive characteristics of cancer cells, including proliferation, metastasis, and chemoresistance." (PMID 41373666, 2025). "Claudin-2 (CLDN-2) and claudin-4 (CLDN-4) are leaky-type tight junction proteins, and their overexpression increases the tumorigenesis of some types of cancer cells." (PMID 38338691, 2024). "Moreover, both of the cell lines were characterized by lower expression of claudin-2 (CLDN2), C-X-C chemokine receptor type 4 (CXCR4), and cytochrome P450 family 24 subfamily A member 1 (CYP24A1), which codify for proteins commonly reported to be associated with cancer progression and invasiveness." (PMID 35159043, 2022). "Claudin‐2 (CLDN2), as a component of cellular tight junction, is reported to participate in the progression of various cancers through its expression aberrance." (PMID 34965023, 2021). "Claudins are solely involved in tight junctions and critical for cell‐to‐cell adhesion in epithelial cells, CLDN2 and CLDN7 have been shown to facilitate the adhesion of cancer cells to the ECM, which is important for cancer metastasis." (PMID 33377642, 2020). "Following this initial profiling of claudin-2 expression in human CRC, we focused on the expression of claudin-2 in cancer cells and CAFs." (PMID 29134439, 2018). "Here we propose a mechanism for this effect by which miR-30a counteracts the aggressiveness and metastasis of cancer cells by increasing tight junction molecules—CLDN-1, CLDN-2, and CLDN-3—via targeting the 3′-UTR of Slug mRNA." (PMID 26918943, 2016). "Therefore, claudin-2 may be not only a novel biomarker but also a therapeutic target of cancer." (PMID 26061016, 2015). "The representative genes used were ALDH3A1, TNS4, CLDN2, and ALDKETO, and are known to play important roles in cancer cell de-differentiation, migration, invasion, proliferation and apoptosis suppression." (PMID 24884630, 2014). "The expression of some genes, such as ALDH3A1, TNS4, CLDN2, and AKR1B10, which are known to play important roles in cancer cell migration, invasion, proliferation and apoptosis, were increased in HCT-8 R cells." (PMID 24884630, 2014). "Cellular senescence refers to a state of irreversible cell cycle arrest, indicating the CLDN2+ AT2 cells were in a stationary state and cannot divide indefinitely and thus may prevent the metastasis of the cancer cells in MPLCs." (PMID 37488117, 2023). "Our current results indicate that such cancer cell/hepatocyte interactions do not rely on the PDZ-binding motif of Claudin-2." (PMID 34079064, 2021). "Combining the essential role of NDRG1 in cancer metastasis inhibition, we sequentially validated its negative correlation with CLDN2 expression as indicated by western blot and Pierson correlation analyses." (PMID 34965023, 2021). "Interestingly, this analysis demonstrated a significant decrease in claudin-2 expression in RCC patient samples and also that this decrease was specific to the cancer stages/progression." (PMID 33622361, 2021).
cancer (continued). "Taking into account that CLDN2 expression has been shown to be downregulated by non-steroid anti-inflammatory drugs, it makes it a promising molecular target for cancer chemoprevention and warrants further in-depth functional studies on the protein." (PMID 32630408, 2020). "In the following sections, we will provide an overview of the evidence linking claudin-2 to cancer, and various non-malignant pathologies, such as inflammatory gastrointestinal and kidney diseases." (PMID 31726679, 2019). "The claudin-2 promoter is activated by both Cdx1 and 2, which might mediate the effects of the ERK pathway in cancer cells." (PMID 31726679, 2019). "No cancer-derived Claudin-2 was detected in EVs isolated from patients possessing benign lesions." (PMID 34079064, 2021).
infection (27 papers, 2013 to 2025). The state of being infected such as from the introduction of a foreign agent such as serum, vaccine, antigenic substance or organism. "Infection with Aa and/or Sg induced changes in the transcriptional profile of genes encoding TJ proteins claudin 1, claudin 2, and occludin and the anchoring protein zonulin in the intestinal barrier." (PMID 39125663, 2024). "Key genes responsible for maintaining epithelial integrity and promoting recovery, such as those encoding claudin-2, e-cadherin, and β1-integrin, displayed reduced expression during infection in Il22−/− mice." (PMID 38557196, 2024). "Strikingly, the increase in claudin-2 levels in Ptpn2∆IEC was reversed after mAIEC infection, with these mice displaying a significant reduction in claudin-2." (PMID 40955058, 2025). "During T. spiralis infection, the expression of the gut epithelial TJ proteins occludin and claudin-3 was found to be downregulated beginning at 2 days post-infection, whereas claudin-2 was overexpressed." (PMID 35255974, 2022). "In our analysis, Claudin-2 was downregulated and structurally disorganized within CP epithelial cells, displaying a ruffled shape upon infection." (PMID 35027063, 2022). "As shown, claudin-2 and claudin-3 proteins were expressed in the OE-129WT cells, and their expression levels either remained steady or were increased late during infection, while claudin-1 protein expression appeared to be diminished after the 20hr time-point." (PMID 30625140, 2019). "Investigations of tight junction proteins in the same experimental setting using immunostaining revealed infection-induced alterations in claudin-1, claudin-2 and in occludin expressions." (PMID 30837987, 2019). "After infection the typical chicken wire pattern of claudin-1 and claudin-2 disappeared and the proteins formed conglomerates." (PMID 30837987, 2019). "We also detected a discrete reduction of ZO-1 (encoded by Tjp1) expression upon infection, without change and in the levels of Claudin-2 and Claudin-11." (PMID 35027063, 2022). "The infection of C. perfringens can increase the expression of claudin-2 in intestine of broilers, which may be explained as a result of ‘cross-talk’ caused by IL-6 among JAK/STAT, SAP/MAPK and PI3K signaling pathways." (PMID 35436978, 2022). "However, claudin-2 protein expression was decreased and fully restored to control levels by resveratrol, while claudin-1 expression was increased after infection and was unchanged by resveratrol." (PMID 33935732, 2021). "C83091 infection stimulated pBD-2, claudin-1 and claudin-2 mRNA expression in IPEC-J2 cells." (PMID 31221216, 2019). "In addition, in EcN + C. jejuni, the expression of the CLDN2, CLDN4, and CLDN11 encoding genes was down-regulated in comparison to infection with C. jejuni." (PMID 28878749, 2017). "In addition, in EcN + C. jejuni, the expression of the CLDN2, CLDN4, and CLDN11 encoding genes was up-regulated in comparison to infection with C. jejuni." (PMID 28878749, 2017). "Interestingly, pre-treatment of OE-TLR3(-) cells with IFN-β prior to infection appeared to mildly but significantly increase the synthesis and stability of claudin-3 at the 20hr time point, while substantially bolstering the synthesis and stability of claudin-1 and claudin-2 throughout infection." (PMID 30625140, 2019). "Phosphorylation sites identified within CLDN2, CX32, and ZO-1 also revealed some crucial points that can be targeted by H. pylori during infection." (PMID 28932213, 2017). "The epithelial marker genes, including γ-GT1, claudin-2, and SLC6A13, were downregulated by TGF-β1 stimulation for 48 h, and then began to increase significantly from 12 h to 18 h after Ad-HNF1B infection." (PMID 27196561, 2016).
infection (continued). "In the current study, FML upregulated the expression of intestinal barrier genes in the duodenum (MUC 1) and ileum (claudin 1 and claudin 2), suggesting that FML enhances the integrity of the mucous layer and generates a host-friendly gut environment to defend against pathogen infection." (PMID 39409860, 2024). "A lack of VDR regulation results in a stout increase of Claudin-2 at the mRNA and protein levels post-infection." (PMID 36678175, 2023). "Only 2 of the 12 up-regulated ISGs (CXCL10 and IFI16) and 2 of the 4 down-regulated (CLDN2 and MX1) were common between HEV-3c and HEV-3f infection, suggesting that the IFN response might differ depending on the HEV subtype involved in infected swine." (PMID 38058490, 2023). "ZO-1 and Claudin-2 showed a poor and non-continuous distribution, characterized by strand breaks and puncta upon infection, compared to naïve controls." (PMID 35027063, 2022). "Claudin-2 transcription was not very different between the two cell types, and its expression was also slightly downregulated early and mid-infection in both OE cell types." (PMID 30625140, 2019). "Interestingly, the increased background claudin-2 in Ptpn2∆IEC mice did not mediate a predicted protective effect against infection." (PMID 40955058, 2025). "Furthermore, the expression of other tight junction protein, such as CLDN2 and OCLN genes, were also significantly altered by the infection in conventional chickens compared to non-infected ones." (PMID 37680750, 2023).
adenocarcinoma (6 papers, 2009 to 2024). A common cancer characterized by the presence of malignant glandular cells. "RT-PCR confirmed that amphiregulin (Areg), epiregulin (Ereg), fetuin beta (Fetub), claudin 2 (Cldn2), hepatic nuclear factor 4, alpha (Hnf4α), glutathione S-transferase, alpha 4 (Gsta4) and forkhead box A3 (Foxa3) were up-regulated in adenocarcinoma." (PMID 19812696, 2009). "We found Cldn2 (13.4-fold) significantly up-regulated in adenocarcinoma." (PMID 19812696, 2009). "Claudin-2 and miR-16 may be potential therapeutic targets for the treatment of adenocarcinomas." (PMID 26061016, 2015).